STEAP4 (STEAP4 metalloreductase)
Diseases named in the same sentence as STEAP4 in open-access papers (continued):
Sharing a sentence is not in itself a finding about the gene and the disease.
diabetes (5 papers, 2015 to 2025). "The results provide strong evidence that diabetes mediates the upregulation of STEAP4 and iron uptake in the murine retina." (PMID 40002391, 2025). "The mechanistic basis for these reported inhibitory and inductive roles of STEAP4 in diabetes onset remains unclear." (PMID 40002391, 2025). "Thus, defining the role of STEAP4 in the development of diabetic retinopathy in STZ-diabetic mice removes the extrinsic factors that could impede the onset of diabetes, thus halting the onset of diabetic retinopathy in wild-type diabetic mice." (PMID 40002391, 2025). "In conclusion, diabetes initiates STEAP4 upregulation in PBMC that circulates through the retinal vasculature, iron (Fe3+) uptake in the retina, and increased STEAP4 in Müller glia and photoreceptors in the retina." (PMID 40002391, 2025). "STEAP4 (green) was prevalently upregulated in the neural retina layers (PRL: red arrows, and INL stretching to IPL and OPL: red box) of the diabetic retina." (PMID 40002391, 2025). "Per Metamorph analyses of all retinas (n = 5/group), levels of STEAP4 are significantly increased in the entire retina of diabetic than in non-diabetic mice; 2-months post-diabetes." (PMID 40002391, 2025). "Note that diabetes and vector did not affect whereas Steap4 overexpression increased Steap4 protein expression." (PMID 25817898, 2015). "There is lacking consensus on the role of STEAP4 in adipocytes and diabetes onset." (PMID 40002391, 2025).
rheumatoid arthritis (4 papers, 2009 to 2025). A chronic, systemic autoimmune disorder characterized by inflammation in the synovial membranes and articular surfaces. "In rheumatoid arthritis and sepsis, upregulated STEAP4 expression in PBMC initiated ROS production that caused pathologic oxidative stress." (PMID 40002391, 2025). "Another group identified v-STEAP4 in CD14+ monocytes from patients with rheumatoid arthritis (RA) and suggested that v-STEAP4 was expressed in the nuclear fraction of THP-1 cells overexpressing v-STEAP4." (PMID 36140186, 2022).
colorectal cancer (3 papers, 2018 to 2024). A primary or metastatic malignant neoplasm that affects the colon or rectum. "Steap4 was reported as a potential marker for immune infiltration in colorectal cancer." (PMID 38533053, 2024).
diabetic retinopathy (3 papers, 2023 to 2025). "Collectively, the results from the human ex vivo and murine in vivo studies reveal the relevance of our original discovery that levels of STEAP4 significantly increase in correlation to the severity of diabetic retinopathy." (PMID 40002391, 2025). "On the contrary, miR-301a-3p is increased in retinal tissue of diabetic retinopathy mouse model and promotes ROS production by inhibiting six-transmembrane epithelial antigen of prostate 4 (STEAP4)." (PMID 37660030, 2023). "Although the role of STEAP4 in the diabetic retina is unclear, these results provide strong evidence that this metabolic enzyme could be a potential biomarker for diabetic retinopathy progression." (PMID 40002391, 2025). "Thus, STEAP4 enhances retinal oxidative stress, which is a pivotal precursor to retinal pathogenesis and the development of diabetic retinopathy." (PMID 40002391, 2025). "Thus, STEAP4 could be a clinically relevant biomarker for the progression of diabetic retinopathy and a novel therapeutic target for the development of diabetic retinopathy." (PMID 40002391, 2025). "Thus, STEAP4 could be a potentially novel therapeutic target and/or a clinically relevant biomarker for the development of diabetic retinopathy." (PMID 40002391, 2025).
head and neck cancer (3 papers, 2020 to 2024). A primary or metastatic malignant neoplasm affecting the head and neck. "While UNC13C and STEAP4 mutations have been found human head and neck cancers, their role in oral carcinogenesis remains unclear." (PMID 32131500, 2020). "One-way Cox regression analysis indicated that STEAP4 acted as a protective factor in head and neck cancer (HNC)." (PMID 39668818, 2024). "Meanwhile, bioinformatics analysis has also revealed that the transcription level of STEAP4 in head and neck cancer tissues is reduced compared with normal tissues, and a low level of STEAP4 resulted in poor disease-free survival, progression-free survival and OS." (PMID 34778263, 2021).
non-alcoholic fatty liver disease (3 papers, 2018 to 2024). "To further explore the association between STEAP1 and STEAP4 with the development of HCC, we analyzed the correlation between their expression with some particular etiology (alcohol consumption, hepatitis, non-alcoholic fatty liver disease) and liver fibrosis (including cirrhosis) in HCC." (PMID 38191397, 2024).
bladder cancer (2 papers, 2020 to 2021). "In bladder cancers, low STEAP4 expression was found in cancer tissues compared with normal, and the circular RNA circPICALM competed with STEAP4 for binding to miR-1265 to eliminate the enhancing effect of miR-1265 on invasion." (PMID 34778263, 2021).
ductal breast carcinoma (2 papers, 2020 to 2021). "The mRNA level of STEAP4 was also decreased in tissues of ductal breast carcinoma, compared with normal tissues, with -7.186 fold change (p = 1.34e − 7)." (PMID 32802887, 2020).
hyperglycaemia (2 papers, 2015 to 2025). "While elucidating that 5 μg of anti-STEAP4 is sufficient to halt hyperglycemia-mediated ROS." (PMID 40002391, 2025). "Interestingly, Steap4-knockout mice develop insulin resistance, hyperglycaemia and inflammation." (PMID 25817898, 2015).
adenoma (1 paper, 2025). A neoplasm arising from the epithelium. "Hematoxylin and Eosin (H&E) staining demonstrated a notable reduction in the percentage of low-grade adenoma after STEAP4 depletion." (PMID 40205952, 2025).
allergic asthma (1 paper, 2024). A asthma with a basis in a pathological type I hypersensitivity reaction. "In order to investigate the potential connection between STEAP4 levels and the development of allergic asthma and MIF levels, rAAV6-STEAP4 was injected into the airways of sensitized mice using a pulmonary administration device." (PMID 39176391, 2024).
asthma (1 paper, 2024). "Accordingly, the present study utilizes three advanced machine learning techniques to effectively identify six-transmembrane epithelial antigen of prostate 4 (STEAP4), a crucial gene associated with asthma, from AEC microarray datasets." (PMID 39176391, 2024). "The expression level of STEAP4 was confirmed to be reduced in the AECs of individuals with asthma and was inversely associated with the severity of the condition." (PMID 39176391, 2024). "As observed, the Th2 inflammatory response in asthmatic mice led to a gradual decrease in the levels of STEAP4 protein and mRNA in airway epithelial cells, which was negatively correlated with the severity of asthma." (PMID 39176391, 2024). "STEAP4 was found to have the potential to serve as a biomarker and be an effective therapeutic target for asthma." (PMID 39176391, 2024). "Furthermore, in the test set, the expression level of the STEAP4 gene decreased in proportion to the severity of asthma, providing additional confirmation of the precision and consistency of this biomarker." (PMID 39176391, 2024). "This suggests that asthma mice with AECs overexpressing STEAP4 were successfully created." (PMID 39176391, 2024).
breast adenocarcinoma (1 paper, 2024). "Among various diseases, the expression of STEAP4 was found to be elevated in luminal breast tumor and colon mucinous adenocarcinoma, but decreased in chronic lymphocytic leukemia, HNSCC, and breast adenocarcinoma." (PMID 39668818, 2024).
experimental autoimmune encephalomyelitis (1 paper, 2021). An autoimmune demyelinating disease of the central nervous system that is produced experimentally in animals by the injection of homogenized brain or spinal cord in Freund's adjuvant. "Here, we report that the metalloreductase, STEAP4, is a key effector molecule that participates and contributes to the pathogenesis of Th17-mediated neuroinflammation in experimental autoimmune encephalomyelitis." (PMID 33879167, 2021).
gastric cancer (1 paper, 2024). A primary or metastatic malignant neoplasm involving the stomach. "Conversely, STEAP4 has been shown to act as an oncogene in gastric cancer, and is strongly associated with poor prognosis in patients." (PMID 39668818, 2024).
generalized pustular psoriasis (1 paper, 2025). A rare and extreme form of psoriasis characterized by the appearance of sterile pustules which can take many patterns. "Moreover, cellular copper uptake is primarily regulated through the IL-17-STEAP4 axis, with elevated STEAP4 expression observed in keratinocytes of patients with generalized pustular psoriasis." (PMID 40332377, 2025).
head and neck squamous cell carcinoma (1 paper, 2024). A squamous cell carcinoma that arises from any of the following anatomic sites: lip and oral cavity, nasal cavity, paranasal sinuses, pharynx, larynx, and salivary glands. "Publicly available online tools were utilized to analyze the expression, prognostic significance, and related enriched pathways of STEAP4 in head and neck squamous cell carcinoma (HNSCC) and OSCC." (PMID 39668818, 2024).
lentivirus infection (1 paper, 2025). Virus diseases caused by the Lentivirus genus. "Subsequently, STEAP4 knockdown in naïve CD4+ T cells was mediated by lentivirus infection." (PMID 41422349, 2025). "Following lentivirus infection, naïve CD4+ T cells were subjected to Th2 polarization conditions, and we observed the decreased STEAP4 protein expression in Th2 cells with STEAP4 knockdown." (PMID 41422349, 2025).
liver disease (1 paper, 2025). "As shown in the heat map, male offspring exposed to HSD exhibited differential expression of ten genes associated with liver disease compared to normal offspring: Ager, Dph1, Steap4, Nfe2l1, Ppara, Rbmx, Nr1d1, Ccar2, Axl, and Abcg5." (PMID 41036197, 2025).
liver fibrosis (1 paper, 2024). "The results showed that STEAP1, STEAP4, and risk score were not correlated with specific etiology, while STEAP1 and risk score were significantly positively correlated with liver fibrosis both in TCGA and GSE14520." (PMID 38191397, 2024).
Miscarriage (1 paper, 2025). A pregnancy that ends at a stage in which the fetus is incapable of surviving on its own, defined as the spontaneous loss of a fetus before the 22th week of pregnancy. "STEAP4 up-regulates intracellular Cu+ ion levels and causes cuproptosis, which further induces miscarriage." (PMID 40855689, 2025).
ocular hypertension (1 paper, 2024). Abnormally high intraocular pressure. "Gene expression of signature astrocyte reactivity markers (Gfap, Lcn2, Steap4, Gbp2, Serping1, and Fbln5) were significantly upregulated in response to ocular hypertension at 2, 4, and 8 weeks compared to that in normotensive controls." (PMID 38610040, 2024).
oral cancers (1 paper, 2024). "According to the AJCC 7th edition clinical staging of oral cancers, STEAP4 expression was higher in stage 3 and above." (PMID 39668818, 2024).
psoriasis (1 paper, 2025). An autoimmune condition characterized by red, well-delineated plaques with silvery scales that are usually on the extensor surfaces and scalp. "Indeed, serum STEAP4 levels are consistently higher in psoriasis patients compared to healthy controls, suggesting a potential mechanistic link between cuproptosis and the IL-17 inflammatory cascade." (PMID 40332377, 2025).
virus infection (1 paper, 2025). "Stable Steap4 knockdown in MC38 cells was achieved through virus infection, validated by western blot analysis." (PMID 40205952, 2025).
tumor (23 papers, 2015 to 2026). "Using the same mouse model, HIF2α was demonstrated to also trigger the activation of the iron reductase six-transmembrane epithelial antigen of the prostate 4 (STEAP4), causing mitochondrial iron accumulation, elevated ROS levels, and increased tumor burden." (PMID 37273145, 2023). "In light of the impact of STEAP4 expression on tumor growth, we sought to determine the role of STEAP4 in mouse colon epithelial cells in the colitis-associated cancer model." (PMID 32060280, 2020). "Immunofluorescent analysis of the AOM-DSS-induced tumors showed that STEAP4 deficiency resulted in a reduced frequency of Ki67-positive and an increased frequency of active caspase-3-positive tumor cells." (PMID 32060280, 2020). "Steap4 deficiency resulted in pronounced reduction of copper and iron accumulation in enriched colonic epithelial cells, and the tumor burden in the Steap4CKO mice was also reduced compared to their littermate controls." (PMID 32060280, 2020). "Notably, STEAP4 deficiency resulted in decreased gross tumor growth, reduced tumor number, fewer tumors at specific sizes (1–2 mm and 3–4 mm) and diminished tumor burden." (PMID 40205952, 2025). "STEAP4 expression was significantly associated with the tumor grade (p < 0.01)." (PMID 33842315, 2021). "Given the well-documented role of IL-17 signaling in driving epithelial cell proliferation and survival in inflammation-associated tumorigenesis, we asked whether STEAP4-mediated copper uptake promotes tumor growth." (PMID 32060280, 2020). "This highlights a potential therapeutic avenue for selectively targeting tumor cells with high STEAP4 expression." (PMID 40205952, 2025). "To validate the presence of STEAP4+ myoCAF in PCa patients, we applied flow cytometry to seperate STEAP4+ myoCAF from tumor tissue and validated the isolation of STEAP4+ myoCAF by immunofluorescence." (PMID 40917018, 2025). "The impact of STEAP4 on tumor growth was further validated in xenograft models, in which STEAP4 knockdown led to significant suppression of tumor growth." (PMID 40205952, 2025). "Representative immunofluorescent staining images demonstrated distinct STEAP4+ myoCAF expression levels across tumor samples." (PMID 40917018, 2025). "Quantitative PCR (qPCR) analysis revealed a significant decrease in Steap4 expression in normal and tumor colon tissues of Steap4 knockout mice compared to those of Steap4 wild-type mice." (PMID 40205952, 2025). "Subsequent studies should evaluate the efficacy of NQO1 bioactivatable drugs, such as β-LPC and KP372-1, in selectively targeting tumor cells with high STEAP4 expression using patient-derived models and mouse models." (PMID 40205952, 2025). "Our findings unveiled the tumor heterogeneity of STEAP4 in OSCC, highlighting its potential as an independent predictor of OSCC prognosis." (PMID 39668818, 2024). "We discovered that STEAP4, as a metalloreductase, exhibits unique tumor heterogeneity in different cancer types and subtypes." (PMID 39668818, 2024). "In summary, our research verified that STEAP4 exhibits tumor heterogeneity in HNSCC and OSCC and can serve as an independent predictor for assessing the prognosis of OSCC patients." (PMID 39668818, 2024). "IL-22 has previously been reported to promote liver regeneration, while facilitating tumor development in the liver via Steap4 upregulation." (PMID 38533053, 2024). "Taken together, IL-22-regulated Il33 was specifically related to hepatocyte proliferation, whereas Steap4 was involved both in hepatocyte proliferation and tumor progression." (PMID 38533053, 2024). "TUNEL assay also showed inhibition of AKT, and STEAP4 also promoted DDP-induced apoptosis in tumor tissues." (PMID 38111065, 2023).
tumor (continued). "Our study has identified STEAP4 as a regulatory node for inflammation-mediated cellular copper uptake and revealed a mechanism through which inflammation and copper promote tumor progression." (PMID 32060280, 2020). "Taken together, the data indicate that STEAP4-mediated copper uptake plays a crucial role in promoting tumor growth." (PMID 32060280, 2020). "Taken together, these data demonstrate a critical role for STEAP4-mediated copper uptake in tumor initiation and cancer progression." (PMID 32060280, 2020). "In line with the in vitro data, inhibition of NFκB activation reduced tumor cell proliferation and attenuated the growth advantage conferred by STEAP4 expression in the xenograft model." (PMID 32060280, 2020). "Again, the dysregulation of CEP55, CLDN4, CHAF1A, H19 and STEAP4 have been found to significantly correlate with CRC tumor stage, aggressiveness, metastasis and poor prognosis." (PMID 30823889, 2019). "Collectively, these findings highlight consistent transcriptional alterations in PBMCs and tumor tissues and suggest that STEAP4, EPC1, and CLEC1B may serve as potential non-invasive biomarkers with diagnostic and prognostic relevance in HCC." (PMID 41909879, 2026). "Integration of PBMC and tumor profiles identified STEAP4, EPC1, CLEC1B, and LCN2 as shared DEGs." (PMID 41909879, 2026). "This implies that in addition to secreting NRG1, chemokines, and inflammatory factors, STEAP4+ myoCAF may also secrete specific lipids to facilitate tumor cell proliferation and survival under the selective pressure of enzalutamide." (PMID 40917018, 2025). "The results identified two major trajectories: RGS5+ fibroblasts and MYH11+ fibroblasts acted as progenitors, whereas STEAP4+ fibroblasts and Tumor-like fibroblasts represented transitional states, terminally evolving into ECM-remodeling fibroblasts or C7+ fibroblasts." (PMID 40520021, 2025). "This phenomenon suggests considerable variation in STEAP4 expression among different oral mucosal tissues, which may contribute to the tumor heterogeneity of STEAP4 in OSCC." (PMID 39668818, 2024). "STEAP4 was found to contain tumor suppressor activity in several human malignancies." (PMID 38206124, 2024). "A study showed that STEAP4 is significantly hypermethylated in HCC tumours, and its epigenetic silencing may be related to HCC." (PMID 35513781, 2022). "STEAP family members in different cancers are irregularly expressed and participate in the proliferation, migration, invasion, apoptosis, and prognosis of cancer cells, although STEAP3 and STEAP4 may have tumor suppressor functions in cancers." (PMID 34778263, 2021). "Our mechanistic findings suggested that expression of STEAP4 might promote tumor growth via multiple downstream pathways." (PMID 32060280, 2020). "Consistently, immunofluorescence staining revealed that while s63845 treatment increased caspase-3 activation in both STEAP4-expressing xenograft tissue and control tumor tissue, STEAP4 expression was able to reduce the frequencies of cleaved caspase-3-positive cells in s63845-treated tumor." (PMID 32060280, 2020). "Furthermore, STEAP4 was readily induced by tumor-promoting cytokines such as IL-17, and the expression of STEAP4 was required for IL-17-induced elevation of copper uptake." (PMID 32060280, 2020). "Notably, the expression of STEAP4 in HNSCC tended to be decreased in advanced tumor stages." (PMID 39668818, 2024). "Compared to those in normal tissues, APOE, STEAP4, and C1QTNF3 expressions were upregulated in tumor tissues, whereas BNIP3L and PPARGC1A expressions were downregulated." (PMID 39524226, 2024). "More importantly, STEAP4 and ADGRF5 specifically expressed in subgroup 3 and 4 showed a significant overexpression of CXCR4 and SRGN, which were closely related to tumor metastasis or immunosuppression in TME." (PMID 37221625, 2023).